EGFR (epidermal growth factor receptor)
Diseases named in the same sentence as EGFR in open-access papers (continued):
Sharing a sentence is not in itself a finding about the gene and the disease.
esophageal cancer (continued). "In esophageal cancer, NAT10 enhances the abundance of ac4 C-modified tRNAs and further enhances the translation efficiencies of EGFR, which is a member of receptor tyrosine kinase family and is activated by various ligands to mediate various cellular activities to promote cancer progression." (PMID 40588654, 2025). "The overexpression of Epidermal Growth Factor Receptor (EGFR), Erb-B2 Receptor Tyrosine Kinase 2 (HER2), and Vascular Endothelial Growth Factor Receptor (VEGFR) has been reported in esophageal cancer, which enhances tumor occurrence, progression, and drug resistance." (PMID 35463306, 2022). "However, the top ranking list of oncogene focal amplifications was different between esophageal cancer and GCAs, where CCND1 and EGFR were the top two ranking oncogene focal amplifications in the esophageal cancer." (PMID 34764264, 2021). "RNA-seq data from TCGA database confirmed that EGFR expression is indeed significantly higher in tumors than that in adjacent non-tumor tissues in esophageal cancer patients." (PMID 34722266, 2021). "In our present study, the results were shown that lncRNA LINC00152 knock-down could inhibit EGFR/PI3K/AKT pathway and stimulate P21 expression in esophageal cancer cell lines (Eca 109 and Kyse 150) in vitro study." (PMID 32190735, 2020). "As for other esophageal cancer cell lines, most cells have higher EGFR expression levels than that of KYSE14021, which suggests that this chip may be used to isolate CTCs from many types of esophageal cancer." (PMID 30104638, 2018). "Furthermore, consistent with a recent study in esophageal cancer, verteporfin diminished both total and phospho-YAP1 levels and EGFR expression, both alone and in combination with cisplatin or erlotinib or radiation treatment." (PMID 26716514, 2016). "The COG study, a phase III, randomised, double blinded trial of gefitinib, a tyrosine kinase inhibitor targeting EGFR, versus placebo in the second line setting of esophageal cancer patients did not demonstrate improvement in overall survival." (PMID 26478746, 2015). "However, a previous phase II study of gefitinib as a second-line treatment for advanced esophageal cancer reported a significantly higher disease control rate (response and SD) in patients with ESCC expressing high levels of EGFR." (PMID 26392415, 2015). "Therefore, an agent targeting both EGFR and HER2 would exhibit more effective therapeutic effects on esophageal cancer patients." (PMID 24664246, 2014). "Furthermore, overexpression of both EGFR and HER2 was observed in 18%–25% patients with esophageal cancer." (PMID 24664246, 2014). "ALA-PDT enhances the effect of the EGFR inhibitor AG1478 and the PI34 inhibitor LY294002, significantly reducing the expression of EGFR/PI3K and PI3K/AKT proteins, leading to a synergistic reduction in the growth and migration ability of Eca-109 esophageal cancer cells in vitro." (PMID 38201494, 2023). "Of course, it should be noted that targeting inhibition of p-EGFR/IMPDH2 signaling may be able to improve esophageal cancer treatment efficacy, and the question as to whether there is a relationship between IMPDH2 and EGFR signaling requires in-depth experimental exploration." (PMID 35416106, 2022). "It is easy to understand that esophageal cancer patients without high EGFR expression may not benefit from EGFR inhibition." (PMID 30477458, 2018). "We chose two cell lines of the two main histotypes of esophageal cancer, esophageal adenocarcinomas (EACs) and esophageal squamous cell carcinomas (ESCCs), which are characterized by divergent overexpression of the two targeted receptors, EGF-receptor (EGFR) and HER2." (PMID 28128281, 2017). "And some scholars believe that the length of the survival of esophageal cancer patients was independent of EGFR overexpression, or at least it could not be an independent prognostic factor." (PMID 26099724, 2015).
esophageal cancer (continued). "Furthermore, our current multivariate analysis showed that EGFR expression and lymph node status were independent prognostic factors to predict survival of esophageal cancer patients, whereas tumor stage was not able to predict survival." (PMID 24131756, 2013). "Here we have analyzed EGFR mutations in EGFR TK domain (exons 18 to 21) in a total number of 152 ESCC from Iran and India (Kashmir), two areas of the “Asian Esophageal Cancer Belt” where smoking and alcohol drinking are not significant risk factors at population level." (PMID 23244191, 2012). "This study aims to develop and validate a prediction model for non-operative, epidermal growth factor receptor (EGFR)-positive, locally advanced elderly esophageal cancer (LAEEC)." (PMID 37251922, 2023). "Although several clinical studies show the beneficial effects of EGFR inhibitors in the treatment of ESCC, evidence supporting the validity of EGFR-targeting therapies for esophageal cancer is not robust." (PMID 28764725, 2017).
liver cancer (159 papers, 2008 to 2026). An epithelial or non-epithelial malignant neoplasm that arises from the liver. "One important finding is that EGFR hyperactivation is not only associated with poor prognosis in liver cancer but also associated with increased sensitivity to afatinib in both cell lines and organoids." (PMID 38154692, 2023). "To verify associations between TAZ signals and activation of EGFR/HER2 signaling pathways in liver cancers, we performed both database and immunohistochemistry (IHC) analyses." (PMID 35439973, 2022). "ADAM17 is found to be overexpressed in a large set of tumors, including breast, colon and liver cancer, and has been linked to autocrine activation of epidermal growth factor receptor (EGFR) on tumor cells." (PMID 36078095, 2022). "We further found that the resistance of EGFR-overexpressed liver cancer cells to sorafenib is associated with low activity of AMP-activated protein kinase (AMPK) and CCAAT/enhancer binding protein delta (CEBPD) as well as insufficient autophagic activation." (PMID 33681180, 2021). "Epidermal growth factor receptor (EGFR) amplification and its abnormal activity are tightly linked to the occurrence and development of various malignant tumors including liver cancer." (PMID 32298294, 2020). "The discovery of mutations in BRAF (B-Raf proto-oncogene, a serine/threonine kinase) and EGFR (epidermal growth factor receptor) by DNA sequencing contributed to the development of new targeted therapies for liver cancer patients carrying these mutations." (PMID 32280695, 2020). "This lncRNA was shown to regulate EGFR expression in liver cancer, and most recently, expression of this lncRNA has been shown to be associated with sensitivity to EGFR TKIs in patients with head and neck SCC (HNSCC)." (PMID 29701689, 2018). "The EGF receptor (EGFR) plays a link between inflammation and liver cancer, and EGF gene polymorphisms have been reported to be associated with HCC risk." (PMID 22235351, 2012). "Overexpression of SRF promotes the growth and migration of liver cancer cell lines and promotes a mesenchymal phenotype, a feature that has been associated with the resistance of cancer cells to EGFR inhibitors." (PMID 23115635, 2012). "Studies have revealed a significant association between EGFR and liver cancer." (PMID 38473265, 2024). "Furthermore, EGFR deficiency specifically in macrophages has been shown to attenuate liver cancer in a mouse model." (PMID 37859621, 2023). "In this study, the strong activation of EGFR by fisetin in cancer cells might be a vital therapeutic approach for liver cancer treatment associated with the EGFR." (PMID 37996895, 2023). "Moreover, EGFR mutations were frequent in colorectal, lung, prostate, and liver cancers." (PMID 39594421, 2024). "Second, we tested integrin β1, as it is a well‐known co‐receptor for agrin in liver cancer cells.[13a,e] To this end, we observed minimal interactions between agrin, integrin β1, and EGFR in compliant matrices (0.5 kPa)." (PMID 40165020, 2025). "This latter study revealed that using a kinome-based CRISPR/Cas9 genetic screen, it was discovered that inhibition of EGFR is synthetic lethal with Lenvatinib treatment of liver cancer." (PMID 40336047, 2025). "IL‐1β from liver cancer cells activates EGFR signaling in Kupffer cells via ADAM17 (also known as TACE), leading to IL‐6 production through JNK, p38, and IKK signaling." (PMID 40859900, 2025). "In contrast, the authors observed the activation of EGFR by lenvatinib and a synergistic anti-cancer effect of lenvatinib with gefitinib in EGFRhigh liver cancer cells." (PMID 38338736, 2024). "In this study, EREG showed the promotion of the cell proliferation and migration/invasion of Huh7, an EGFR-expressing liver cancer cell line." (PMID 38673992, 2024). "A Western blot analysis revealed that oxymatrine suppresses the expression of EGFR, contributing to its therapeutic efficacy against liver cancer." (PMID 39457402, 2024).
liver cancer (continued). "The EGFR downstream effector RAS is a major oncogenic factor for human cancer, and KRAS mutation is the most frequent isoform among RAS mutations in liver cancer patients." (PMID 38791872, 2024). "As a result, ESR1 and EGFR were identified as potential core targets of CKI for treating liver cancer and were selected for a subsequent experimental analysis." (PMID 39457402, 2024). "Intriguingly, it was suggested that the upregulations of TGFα and EGFR in hepatocytes, particularly in cirrhotic hepatocytes, are induced by a state of hypoxia, supporting their therapeutic potential in liver cancer." (PMID 38473265, 2024). "Thereby, compound 18c exhibited promising cytotoxicity against EGFR/HER2 inhibition against liver cancer." (PMID 37291635, 2023). "Blockage of EGFR signaling with the EGFR monoclonal antibody Cetuximab sensitized tumor cells to Oxaliplatin, indicating that this combination strategy should be re-evaluated in advanced liver cancer." (PMID 37253718, 2023). "Recently, an article published in Nature showed that EGFR activation limits the response of liver cancer to lenvatinib in HCC." (PMID 36973682, 2023). "RNF12 was found to activate PI3K‐AKT signalling to promote the progression of liver cancer by interacting with EGFR." (PMID 37132043, 2023). "Golgi membrane protein 1 (GOLM1), as an oncogene, promoted the growth and metastasis of liver cancer by selectively binding with epidermal growth factor receptor (EGFR)." (PMID 38155974, 2023). "It has been confirmed that EGFR targets have a significant impact on the proliferation and migration of liver cancer cells, which is consistent with the results of network pharmacological analysis in this study." (PMID 37393306, 2023). "In this study, we found that RNF12 activated the PI3K‐AKT signalling pathway by interacting with EGFR to promote liver cancer cell proliferation and invasion in vitro and in vivo." (PMID 37132043, 2023). "The epidermal growth factor receptor (EGFR) has been found to be overexpressed or hyperactivated in the cancer cells of most liver cancer patients as well as be the reason for continuous activation of its downstream signaling of the Ras/Raf/MEK/ERK pathway." (PMID 36176764, 2022). "The EGFR signaling axis has been demonstrated to be important in developing liver diseases such as cirrhosis and liver cancer." (PMID 36297027, 2022). "CRISPR/Cas9 gene screening centered on the kinome has shown that inhibition of epidermal growth factor receptor (EGFR) is synthetic lethal with lenvatinib in liver cancer." (PMID 35189910, 2022). "About 87% of human liver cancer with high YAP/TAZ activity (26 out of 30 cancer samples) showed concomitant activation of the downstream signaling pathways of EGFR/HER2." (PMID 35439973, 2022). "In contrast, 11% of liver cancer samples with minimal YAP/TAZ activity (one out of nine cancer samples) revealed activation of the EGFR/HER2 signaling pathways." (PMID 35439973, 2022). "GSEA using the TCGA database showed enrichments of YAP/TAZ signature gene sets in liver cancers with high levels of phosphorylated EGFR (pEGFR)." (PMID 35439973, 2022). "A previous clinical study reported that the positive rates of EGFR expression were 66.22% in liver cancer, 44.00% in liver cirrhosis, and 10.00% in normal liver tissues." (PMID 36297027, 2022). "The PI3K/AKT signaling pathway is a downstream signaling pathway of epidermal growth factor receptor, which is overexpressed in a variety of malignant tumors, such as breast, ovarian, lung, and liver cancers." (PMID 34765009, 2021).
liver cancer (continued). "The in-vitro data indicated that intracellular contents of ESR1, EGFR mRNAs in oxyresveratrol-treated liver cancer cells were reduced." (PMID 34592904, 2021). "One study revealed that GOLM1 acts as an oncogene promoting liver cancer by adjusting epidermal growth factor receptor/receptor tyrosine kinase (EGFR/RTK) cell-surface recycling." (PMID 33649292, 2021). "In this sense, it has been suggested that the EGFR inhibitor Gefitinib was able to decrease PD-L1 expression and inhibition of T-cell-mediated lysis of liver cancer cells through EGFR activation." (PMID 35008796, 2021). "These validated findings demonstrated that the ESR1, EGFR can be anti-liver cancer pharmacological targets exerted by oxyresveratrol." (PMID 34592904, 2021). "Conversely, MUC15 was downregulated in liver cancer and inhibited liver cancer metastasis by targeting EGFR/PI3K-AKT pathway." (PMID 34539882, 2021). "Considering the fact that most liver cancers express high levels of EGFR, they explored the therapeutic potentials of combinating EGFR targeting gefitinib and lenvatinib in HCC." (PMID 34608130, 2021). "Although little is known about the role of MIG6 in liver cancer, ERRFI1 deletion has been found in 13% of humans with HCC, in contrast to the extremely low incidence (around 1%) of EGFR mutations." (PMID 33806040, 2021). "The previous report showed BJ extract suppressed the growth of liver cancer stem-like cells by attenuating EGFR expression." (PMID 35582384, 2021). "As an example, in a study conducted in human liver cancer cells, treatment with a dietary component, catecholone, inhibited the EGFR-Akt-ERK signaling pathway." (PMID 34572344, 2021). "We further confirmed that EGF signaling is critical for the proliferation of liver cancer cells by EGFR inhibitor SC0186." (PMID 32298294, 2020). "In the current study, VEGFA and EGFR were not only overlapping genes revealed between Xihuang pill target sets and liver cancer target sets but also hub nodes in PPI modules." (PMID 32256653, 2020). "Overexpression of EGFR and its abnormal activity are closely related to the occurrence and development of various malignant tumors including liver cancer." (PMID 32298294, 2020). "EGF is a ligand capable of binding to EGF receptor (EGFR) and regulates cell growth, differentiation, migration, invasion, and tumorigenesis in various cancer types, including liver cancer." (PMID 32376896, 2020). "The expression of this fusion gene induced spontaneous liver cancer in mice by ectopically phosphorylating the EGFR extracellular domain and activating its signaling pathways." (PMID 30705370, 2019). "Samaga and colleagues built a comprehensive logical model of the signalling network of EGFR in liver cancer, which was based on the comprehensive EGFR network map published by Oda and colleagues." (PMID 29671404, 2018). "The EGFR antibody-conjugated iMNPs exhibited specific targeting to EGFR-overexpressed liver cancer cell in vitro, as observed by MRI and CT imaging." (PMID 29017600, 2017). "The iMNP-EGFR particles were applied for the simultaneous multi-imaging of xenograft liver cancer and the successful targeting of EGFR-expressed orthotopic tumor in mouse models." (PMID 29017600, 2017). "Previous analysis of the gene expression profile of a panel of 84 liver cancer-specific genes in C/EBPα-saRNA-transfected HepG2 cells showed that most tumor genes including CTNNB1 (encoding β-catenin) and EGFR involved in EMT were down-regulated." (PMID 27050434, 2016). "Next, we found that EGFR expression is elevated in liver cancer tissues in comparison to normal tissues using TCGA database and expression of EGFR is correlated to expression of miR-203a." (PMID 27244890, 2016). "High expression of EGFR has been observed in numerous human tumors, including lung, colon, breast, head and neck, ovarian, bladder, and liver cancers, and has been shown to correlate with advanced tumor stage and poor clinical prognosis." (PMID 24433534, 2014).